IL13 (interleukin 13)
Diseases named in the same sentence as IL13 in open-access papers (continued):
Sharing a sentence is not in itself a finding about the gene and the disease.
COVID-19 (continued). "Thus, at early stages of SARS-CoV-2 viral infection, IL-13 inhibition at the lung mucosae may help reduce COVID-19 disease severity/progression." (PMID 34027204, 2021). "Therefore, we suspect that COVID-19 patients may display significant lung ILC2-derived IL-13 (although the role of ILC2s during SARS-CoV-2 infection is yet to be fully realized)." (PMID 34027204, 2021). "Additionally, RELMα can be a marker of AAMs, and in combination with the observation of decreased Arg1 may suggest that these macrophages could be downstream of IL-13 signaling during COVID-19." (PMID 34185704, 2021). "Interestingly, it has been proposed that such interventions could be unfavorable in treating COVID-19, in part due to the Th1/Th17 cytokines involved in hyperinflammation, where IL-13/IL-4 inhibition may further bias in immune activity." (PMID 34027204, 2021). "Further analysis of gene importance across the four models revealed that the top four hub genes in COVID-19 were CR1, TNFRSF10C, TAP2, and TGFBI, while the top four hub genes in SS-KCS were CR1, IL13, TAP2, and IL1R2." (PMID 40149556, 2025). "In patients with the PAP phase of COVID-19, an increase in proinflammatory cytokines, namely, IFN-α, TNF-α, G-CSF, IL17A, IL-6, IL1-β, and IL-13, has been confirmed in a number of studies." (PMID 40002929, 2025). "Supervised machine learning algorithm (RF) was used to predict the COVID-19 severity and chronicity based on immune subset profiling and a 14-plex cytokine panel (TNF-a, IL-4, IL-13, IL-2, GM-CSF, sCD40L, CCL5, CCL3, IL-6, IL-10, IFN-g, VEGF, IL-8, and CCL4." (PMID 40657638, 2025). "Thus, in patients with COVID-19, SaO2, hematocrit, and IL-13 may predict clinical improvement." (PMID 40385586, 2025). "COVID-19 exhibited a distinct immunological profile characterized by increased levels of Th1 (IL-12 and IFN-γ) and Th2 (IL-4, IL-5, IL-10, and IL-13) cytokines, along with IL-1β and IL-6, among other markers." (PMID 39408907, 2024). "In a study involving 294 COVID-19 patients, the analysis revealed key post-COVID cytokines—FGF-2, VEGF-A, EGF, IL-12(p70), IL-13, and IL-6—crucial for understanding pathophysiology." (PMID 38793604, 2024). "IL-8, D-dimer, S100B, IL-6, Angpt-2, MMP-8, TNF-R1, u-PAR, u-PA, osteopontin, IL-13, TNF-α, pentraxin-3, P-selectin, fractalkine, and SP-D levels were elevated in critically ill COVID-19 males compared to severe cases." (PMID 39507250, 2024). "GMCSF, IL-13, IL-1β, IL-2, IL-4, and IL-5 were undetectable in the vast majority of both TTP and COVID-19 samples." (PMID 39337495, 2024). "Moreover, it was reported that epithelial surface bound ACE2 expression is inversely associated with the levels of Th2 cytokines (IL-4, IL-5, and IL-13) that could alleviate the viral-induced release of interferons and downregulate the cytokine storm typical of increasing COVID-19 severity." (PMID 38263182, 2024). "Previously, our group has shown an increased level of cytokines in the antigen-specific culture supernatants including IFNγ, IL-2, IL-4, IL-13, and IL-17 in MIS-C in comparison with acute COVID-19 and other infectious diseases." (PMID 38116577, 2023). "COVID-19 patients with ARDS exhibited higher serum levels of all cytokines and chemokines measured (IFNy, TNFa, IL-4, IL-6, IL-7, IL-8, IL-10, IL-13, MIP-1b, and MCP-1) compared to patients with COVID-19 pneumonia without ARDS (data not shown)." (PMID 37293294, 2023). "The potential pathway through which dupilumab helps patients recover from COVID-19 might be that dupilumab restricts the duplication of SARS-CoV-2 and alleviates the abnormal immune responses in AD patients, possibly by blocking the augmented reaction caused by IL-4 and IL-13." (PMID 37240520, 2023). "Our data demonstrate that the serum levels of IL-12, IL-13, IL-18, and IFN-γ are disturbed in patients with severe COVID-19 compared to mild and moderate cases." (PMID 37373331, 2023).
COVID-19 (continued). "The SARS-CoV-2 spike protein enhanced the expression of ACE2 in Beas-2B cells, and the cytokines IL-4 and IL-13 were repressed, whreas TNF-α, IL-12, and IL-17 increased ACE2 expression in Beas-2B cells, which reflects the different risks of severe COVID-19." (PMID 35287354, 2022). "In relation to the groups with SIgA, increased levels of IL-10, IL-13, IL-17A, and IFN-α were found in the COVID-19 group as compared to the values observed in the control group." (PMID 35686128, 2022). "Serum levels of IFNγ, CRP, IL-10, IL-13, IL-6, IP10, MCP-1 and IL-23 were significantly higher in COVID-19 patients than in controls after adjustment for age and BMI." (PMID 36554094, 2022). "In addition, IL-13 upregulates the downstream hyaluronan synthase 1 (Has1) gene and promotes the deposition of hyaluronic acid (HA) polysaccharide in the lung parenchyma, which may be a new mechanism for the development of severe COVID-19." (PMID 36362440, 2022). "Interestingly, IL-13 provided varying levels of protection for each individual donor, suggesting that patient genetic background and/or cytokine profile may play a role in COVID-19 disease heterogeneity." (PMID 35353667, 2022). "In the multiplex cytokine assays, plasma levels of Th2-related soluble factors such as IL-4, IL-5, IL-13, and CCL22 were comparable between the patient with COVID-19 mRNA vaccine-related myopericarditis and healthy controls." (PMID 35251049, 2022). "In contrast, recent studies reported that IL-13 is actually a driver of COVID-19 severity and that, in SC2-infected mice, IL-13 neutralization decreases mortality and disease severity without altering viral load." (PMID 34747367, 2021). "In our patient’s post-COVID-19 cytokine panel, most notable elevations were found in MCP-1, RANTES and IL-13, which are cytokines with emerging roles in bone remodeling and cortical bone formation." (PMID 34110466, 2021). "Meanwhile, COVID-19 displayed an immune profile distinguished by increased Th1 (IL-12, IFN-γ) and Th2 (IL-4, IL-5, IL-10, IL-13) cytokine levels, along with IL-1β, IL-6, CCL11, VEGF, TWEAK, TSLP, MMP-1, and MMP-3." (PMID 33995342, 2021). "Levels of pro-inflammatory (IFN-γ, IL-1β, IL-6, IL-9, IL-12p70, CCL11) and anti-inflammatory (IL-4, IL-5, IL-10, IL-13) cytokines, as well as VEGF, were higher in severely ill COVID-19 patients as compared to pandemic influenza A(H1N1) subjects." (PMID 33995342, 2021). "In addition, some authors hypothesize that cytokines and chemokines involved in T2 immune responses, like IL-13, IL-9 and Macrophage Inflammatory Protein-1 alpha and beta, might counteract the pool of proinflammatory cytokines involved in the pathogenesis of COVID-19." (PMID 33996694, 2021). "In contrast, IL-1β, IL-4, IL-5, IL-12p70, IL-13, IL-17A, CCL11, and VEGF levels predicted severe COVID-19." (PMID 33995342, 2021). "In contrast to enhanced levels of TMPRSS2, T2 inflammation, whether observed in vivo or induced with IL-13 stimulation, precipitated a marked reduction in levels of epithelial ACE2, thus making it difficult to predict how T2 inflammation might affect overall risk for a poor COVID-19 outcome." (PMID 33046696, 2020). "The stimulation of PBMCs from COVID-19 patients with S protein peptides resulted in production of effector or Th1 cytokines (IFN-γ, TNF-α, and IL-2) and, to a lesser extent, Th2 (IL-5, IL-13, IL-9, and IL-10) and Th17 (IL-17A, IL-17F, and IL-22) cytokines." (PMID 32916812, 2020). "In the first phase of the study, participants in the acute phase of COVID-19 presented patterns of elevated inflammation in the form of high concentrations of cytokines such as TNF (TNF–α), LTA (TNF–β), IL–1β, IL–4, IL–6, IL–8, IL–13, and interferon (IFN) –α2." (PMID 40217938, 2025).
COVID-19 (continued). "From a host genetic perspective, elevated levels of IL-6, IL-10, IL-13, MMP-7, ferritin, and D-dimer were observed in COVID-19 patients across all genotypes, with the CC genotype associated with the highest concentrations, suggesting a heightened inflammatory and pro-thrombotic state." (PMID 40733568, 2025). "At 9–12 weeks after disease onset, participants who had initially severe COVID-19 tended to have significantly higher levels of IP10 and sCD163 and lower levels of IL10, IL6, TNFα, IL17 and IL13 compared to those with mild or moderate disease, when adjusting for other covariates." (PMID 39008486, 2024). "The presence of chronic inflammation in hypertensive patients may explain our observation of increased circulating levels of IL-4, IL-5, IL-13, IL-17A, and TNF-β levels during hospitalization in patients with COVID-19 and hypertension in the present study." (PMID 39685774, 2024). "The mediators CCL3, CCL4, CCL2, CCL5, IL-12, IL-15, IL-1Ra, and PDGF were higher in healthy volunteers, while the mediators CCL11, CXCL10, IL-1b, IL-6, TNF-a, IFN-g, IL-17, IL-9, IL-10, IL-13, FGF-basic, G-CSF, GM-CSF, IL-7, and IL-2 were increased in COVID-19 positive patients." (PMID 37903875, 2023). "We also observed COVID-19-specific enrichment of signaling genes such as MAP3K1, which helps activate JNK and ERK pathways, and STAT6, which is involved in IL-4 and IL-13 signaling." (PMID 36992700, 2023). "COVID-19 positive and COVID-19 negative patients had increased levels of IL-1ra, IL-6, IL-8, IL-13, TNF-α, IP-10, MCP-1, MIP-1α, and G-CSF." (PMID 36980378, 2023). "Cytokines unique to COVID-19 cocktails (IL-4, IL-13), but not sACE2, induced mild albuminuria when injected alone in BALB/c mice." (PMID 37040185, 2023). "IL-13, a T2-high inflammatory cytokine, decreases the expression of angiotensin converting enzyme-2 (ACE2) receptor, hindering SARS-CoV-2 entry; finally, poor outcomes have been observed in COVID-19 patients with severe neutrophilic asthma." (PMID 37679779, 2023). "Another immune signature detected in critically ill patients with COVID-19 includes the type 2 cytokines IL-4, IL-5, IL-13, and TSLP, related to noninfectious lung diseases (Choreño-Parra and others 2021)." (PMID 35647937, 2022). "The plasma levels of IL-13 and MIP-1α were significantly lower in the COVID-19 group." (PMID 35222429, 2022). "Instead, the COVID-19 group without SIgA showed an exclusive positive correlation between the salivary levels of IL-13 and IL-12p70." (PMID 35686128, 2022). "The ratio of the serum concentration of sCD40L was clearly elevated and the ratios of TNFβ and IL-13 were slightly elevated in survivors compared to non-surviving severe COVID-19 patients." (PMID 36142255, 2022). "The COVID-19 group had significantly higher plasma levels of IL-1β, IL-4, IL-7, IL-8, IL-12, TNF, IP-10, eotaxin, GM-CSF, bFGF, complement TCC and C3bc, and significantly lower levels of IL-13 and MIP-1α, as compared to controls." (PMID 35222429, 2022). "Furthermore, IL-1Ra, IL-13, PDGF and IL-7 were also identified as promising molecules to distinguish COVID-19 patients progressing to a worse prognosis (MV or Death)." (PMID 36451835, 2022). "Overall, these results demonstrate the ability of a selected set of systemic mediators (IL-6, IFN-γ, IL-1Ra, IL-13, PDGF and IL-7) as putative laboratory markers that are applicable as complementary records in the clinical management of severe COVID-19 patients." (PMID 36451835, 2022). "Several mediators such as Tie-2, VEGFA, IL-17D, IL-3, GM-CSF, IL-1α, IL-5, Eotaxin 3, IL-12p70 and IL-13 were not significantly different between COVID-19 and control subjects (data not shown)." (PMID 36116160, 2022). "In Non-SOT COVID-19 patients, we observed 6 (IL-13, IL-10, IFN-γ, IL-12p70, MCP-2, IL-6) and 9 (IL-16, IL-13, TNF-α, IL-6, IL-18, IL-15, MIP-1α, IL-2Ra, IL-8) cytokine correlations with monocyte and neutrophil derived cfDNA, respectively." (PMID 35075453, 2022).
COVID-19 (continued). "Moreover, a selected set of serum soluble mediators (IL-6, IFN-γ, IL-1Ra, IL-13, PDGF and IL-7) were pointed out as promising biomarkers for the clinical management of severe COVID-19 patients." (PMID 36451835, 2022). "A selected set of systemic mediators (IL-6, IFN-γ, IL-1Ra, IL-13, PDGF and IL-7) were identified as putative laboratory markers, applicable as complementary records for the clinical management of patients with severe COVID-19." (PMID 36451835, 2022). "We concluded that the mechanism by which IL-13 was promoting more severe COVID-19 was not necessarily through the type 2 pathways typically observed in the lung." (PMID 34185704, 2021). "Additionally, in healthy controls, rs233575 SNV of the ACE2 gene showed a negative significant correlation with CD40L, while in COVID-19 patients, the SNV rs233575 of the ACE2 gene showed a negative significant association with IL-13." (PMID 38855114, 2024). "Furthermore, we observed a negative correlation between CD74 serum levels and IL-13, a cytokine that has been recently described to be pathogenetic in COVID-19." (PMID 37568438, 2023). "IP-10, MCP-1, and IL-13 were higher for COVID-19 positive than for COVID-19 negative patients." (PMID 36980378, 2023). "In contrast, IL-13 levels were not affected in severe COVID-19 patients." (PMID 37373331, 2023). "In patients infected with SARS-CoV-2, higher levels of the proinflammatory cytokines IL-1β, IL-6, IL-8, IL-13, IL-17, RANTES, and IFN-γ were found, and these increased cytokines and chemokines mediated the infection immunopathogenesis and played important roles in the progression of COVID-19." (PMID 35893674, 2022). "Of note, treatment with the therapeutic compounds commonly administered to acute COVID-19 patients (the JAK inhibitors baricitinib, ruxolitinib and tofacitinib) were able to restore normal cell viability, proliferation and neurogenesis by targeting the effects of IL12 and IL13." (PMID 36195636, 2022). "In SARS-CoV-2 infected mice, IL-13 inhibition reduced death and disease severity without affecting viral load, denoting an immunopathogenic role for this cytokine in mediating the hyperinflammatory state in COVID-19." (PMID 34647194, 2022). "In addition to these findings, it was observed in the intergroup analysis that the COVID-19 group without SIgA showed higher levels of IL-10, IL-13, and IL-17A than the control group without SIgA." (PMID 35686128, 2022). "Some type 2 cytokines (IL-4, IL-9, IL-13, etc.)have inhibitory effects on the production of proinflammatory cytokines (IL-1β, IL-6, TNF-α, etc.), the overactivation of which have been proposed as a potential key mechanism of protection against COVID-19 to some extent." (PMID 35082829, 2021). "Interestingly, treatment with the compounds commonly administered to acute COVID-19 patients (the Janus kinase inhibitors, baricitinib, ruxolitinib and tofacitinib) were able to restore normal cell viability, proliferation and neurogenesis by targeting the effects of IL12 and IL13." (PMID 36195636, 2022). "However, whether the IL-33/MAPK/STAT3/IL-13 axis plays a positive or negative role in the pathology of COVID-19 requires further exploration." (PMID 36362440, 2022). "Therefore, this association also could be responsible for the lack of association between IL-13 and IL-17, two months after SARS-CoV-2 infection, which led some COVID-19 patients to not present salivary SIgA levels." (PMID 35686128, 2022). "However, we propose that in the context of alleviating severe COVID-19, direct inhibition of IL-13 may yield better disease outcomes rather than targeting a particular upstream determinant of IL-13 expression." (PMID 34027204, 2021). "We identified higher levels of D-dimer, IL-6, IL-8, IL-13, Angpt-2, Pentraxin-3, S100B, MMP-8, and u-PAR in the plasma of critical COVID-19 non-survivors than in that of survivors." (PMID 39507250, 2024).
COVID-19 (continued). "We found increased levels of IL-1ra, IL-6, IL-8, IL-13, TNF-α, IP-10, MCP-1, MIP-1α, and G-CSF in both, COVID-19 negative and COVID-19 positive sepsis patients, as compared to healthy controls." (PMID 36980378, 2023). "The negative correlation between CD74 serum levels and IL-13 found in our study suggests a potential role of CD74 in regulating the IL-13-mediated immune response and inflammation in COVID-19." (PMID 37568438, 2023). "Specifically, high plasma levels of IFN-λ1, IFN-γ, IL-1RA, IL-6, MCP-2, and lower levels of Eotaxin-3, IL-12p70, IL-13, MCP-4, MDC, TARC, were observed both in SOT and Non-SOT COVID-19 patients as compared to HCs." (PMID 35075453, 2022). "Moreover, the IL-15 immunotherapy may be a feasible strategy for COVID-19, as it induces innate immune responses via the induction of NK cells, CD8+ T cells, and T regulatory cells to neutralize Th2 cytokine storms, leading to decreased levels of IL-4, IL-5, and IL-13." (PMID 35679246, 2022). "The reduced levels of myelomonocytic cytokines found in severe COVID-19 survivors are not generalized because serum sCD40L, TNF-beta and IL-13 are increased." (PMID 36142255, 2022). "We have identified 11 cytokine/chemokine differences in both SOT and Non-SOT COVID-19 patients as compared to healthy controls, including cytokines with higher (IFN-λ1, MCP-2, IL-6, IL-1RA, IFN-γ) or lower (Eotaxin-3, MDC, TARC, IL-13, MCP-4, IL-12p70) levels." (PMID 35075453, 2022). "Proinflammatory molecules, such as IL-2, IL-4, IL-5, IL-6, IL-10, IL-13, TNF-α, IFN-Υ, and CRP, were found at higher levels in COVID-19 patients with DM than in COVID-19 patients without DM." (PMID 34786431, 2021). "We found that eight pro-inflammatory factors (IL-6, IL-8, IL-13, IL-1ra, MIP-1a, IP-10) out of 27 analyzed serum cytokines were modulated in COVID-19 patients irrespective of cancer status." (PMID 34716309, 2021).